GSTP1 (glutathione S-transferase pi 1)
Description:
Catalyzes conjugation of reduced glutathione to a wide number of exogenous and endogenous hydrophobic electrophiles. Involved in the formation of glutathione conjugates of both prostaglandin A2 (PGA2) and prostaglandin J2 (PGJ2). Participates in the formation of novel hepoxilin regioisomers. Acts as a negative regulator of ferroptosis by mediating glutathione conjugation and detoxification of 4-hydroxynonenal (4-HNE) reactive aldehyde. Negatively regulates CDK5 activity via p25/p35 translocation to prevent neurodegeneration.
Synonyms: FAEES3; GST3; GSTP; DFN7; GSTP1-1; HEL-S-22; PI
Tractability: Small molecule: a drug acting on it is in phase 2 or 3 trials; a structure with a bound ligand is known; a high-quality ligand is known; it has a high-quality binding pocket; it belongs to a druggable protein family. Antibody: its Gene Ontology location is reachable by antibodies, with high confidence. PROTAC: ubiquitination databases record sites on it; its protein half-life has been measured; a small molecule that binds it is known.
Target class: Enzyme; Transferase
Safety:
Unwanted effects reported when the protein is acted on. In parentheses: how it was acted on, where the effect was seen, and who reports it.
cardiotoxicity (source: ClinPGx)
drug toxicity (source: ClinPGx)
hematological toxicity (source: ClinPGx)
infection (source: ClinPGx)
infection or nausea (source: ClinPGx)
leukopenia (source: ClinPGx)
liver injury (source: ClinPGx)
nausea (source: ClinPGx)
neutropenia (source: ClinPGx)
ototoxicity (source: ClinPGx)
toxicities (source: ClinPGx)
Gene: Protein-coding gene on chromosome 11 (67,583,658 to 67,586,659, forward strand). Ensembl gene ENSG00000084207.
Subcellular location: Cytoplasm; Mitochondrion; Nucleus
Subcellular location (Human Protein Atlas): Cytosol; Mitochondria
Pathways (Reactome):
Cellular responses to stimuli: Detoxification of Reactive Oxygen Species
Drug ADME: Paracetamol ADME
Immune System: Neutrophil degranulation
Metabolism: Glutathione conjugation
Gene Ontology:
Molecular function: dinitrosyl-iron complex binding; fatty acid binding; glutathione peroxidase activity; glutathione transferase activity; protein binding; S-nitrosoglutathione binding; JUN kinase binding; nitric oxide binding; protein serine/threonine kinase inhibitor activity; protein kinase binding; toxic substance binding
Biological process: glutathione derivative biosynthetic process; glutathione metabolic process; hepoxilin biosynthetic process; linoleic acid metabolic process; negative regulation of ERK1 and ERK2 cascade; negative regulation of extrinsic apoptotic signaling pathway; negative regulation of ferroptosis; negative regulation of interleukin-1 beta production; negative regulation of JNK cascade; negative regulation of monocyte chemotactic protein-1 production; negative regulation of tumor necrosis factor production; prostaglandin metabolic process; xenobiotic metabolic process; cellular response to lipopolysaccharide; central nervous system development; common myeloid progenitor cell proliferation; negative regulation of acute inflammatory response; negative regulation of apoptotic process; negative regulation of canonical NF-kappaB signal transduction; negative regulation of fibroblast proliferation; negative regulation of leukocyte proliferation; negative regulation of MAPK cascade; negative regulation of stress-activated MAPK cascade; negative regulation of transcription by RNA polymerase II; negative regulation of tumor necrosis factor-mediated signaling pathway; and 20 more
Cellular component: cytoplasm; cytosol; extracellular exosome; extracellular region; mitochondrion; nucleus; TRAF2-GSTP1 complex; vesicle; ficolin-1-rich granule lumen; secretory granule lumen
Genetic constraint (gnomAD): Loss-of-function variants: 21 observed, 21.39 expected, observed/expected ratio (o/e) 0.98, 90% interval 0.69 to 1.41. The upper end of that interval is the gene's LOEUF score, 1.41, which puts it in group 5 of 6, group 1 being the genes least tolerant of losing a copy. Missense variants: 250 observed, 252.55 expected, observed/expected ratio (o/e) 0.99, 90% interval 0.89 to 1.1. Synonymous variants: 114 observed, 111.45 expected, observed/expected ratio (o/e) 1.02, 90% interval 0.88 to 1.2.
Homologues: Orthologues: chimpanzee GSTP1 (99% identical), macaque GSTP1 (97% identical), rat Gstp1 (86% identical), mouse Gstp1 (85% identical), guinea pig GSTP1 (85% identical), mouse Gstp2 (84% identical), Caenorhabditis elegans gst-10 (32% identical), Caenorhabditis elegans gst-41 (30% identical), Caenorhabditis elegans gst-16 (28% identical), Caenorhabditis elegans gst-11 (27% identical), Caenorhabditis elegans gst-14 (26% identical), Caenorhabditis elegans gst-7 (26% identical), and 30 more. Paralogues in human: GSTA3 (32% identical), GSTA1 (32% identical), GSTM3 (31% identical), GSTA2 (31% identical), GSTA5 (30% identical), GSTA4 (30% identical), GSTM2 (30% identical), GSTM4 (30% identical), GSTM1 (29% identical), GSTM5 (29% identical), HPGDS (22% identical).
Diseases named in the same sentence as GSTP1 in open-access papers:
GSTP1 is named in the same sentence as 320 diseases in open-access papers, as found by Europe PMC text mining. Sharing a sentence is not in itself a finding about the gene and the disease. The quoted sentences say what the papers report.
prostate carcinoma (202 papers, 2004 to 2025). A carcinoma that arises from epithelial cells of the prostate gland. "Individuals with the GSTP1 C haplotype, characterized by the co-occurrence of the GSTP1 Val rs1695 and rs1138272 variants, have a 5.46-fold increased risk of prostate cancer." (PMID 40290119, 2025). "A study has shown that GSTP1 polymorphisms behave differently in different tumors, with the GSTP1a allele being significantly lower in prostate cancer while the GSTP1b allele is significantly higher in bladder and testicular cancer." (PMID 40426879, 2025). "This study provides a genetic basis for the relationship between GSTP1 and prostate cancer risk and analyzes the molecular mechanism of GSTP1 in prostate cancer, but the relationship still needs to be further explored by experiments." (PMID 40426879, 2025). "All of these showed that GSTP1 expression is associated with the development and progression of prostate cancer." (PMID 40426879, 2025). "For example, in prostate cancer, the fifth major cause of cancer-related mortality globally, hypermethylation of certain tumour suppressor genes, such as GSTP1, RARB, APC and RASSF1, has been observed during the early stages of the disease." (PMID 39661598, 2024). "The capability of the BMMs is demonstrated to appositely model the beta values, to objectively identify thresholds and to identify existing and novel DMCs, including those related to genes implicated in prostate cancer, such as GSTP1, RARB and RASSF1." (PMID 39661598, 2024). "Increased hypermethylation of GSTP1, a potential biomarker, has been implicated in the progression of prostate cancer." (PMID 38169591, 2024). "Epigenetic silencing of GSTP1 leads to exposure to long-term oxidative damage and increased accumulation of potentially mutagenic DNA adducts, ultimately causing prostate cancer." (PMID 38031146, 2023). "To evaluate the diagnostic accuracy and utility of GSTP1 methylation as a molecular marker for prostate cancer, we constructed a summary receiver operating characteristic (SROC) curve." (PMID 36747996, 2023). "Other studies have shown that men with at least one version of the SNP in the GSTP1 gene: rs1138272 (*Ala/Val + Val/Val) or rs1695 (*Ile/Val + Val/Val) have an elevated risk of prostate cancer." (PMID 37819495, 2023). "Functional inactivation of GSTP1 increases susceptibility to oxidative stress and increases the risk of progression of prostate cancer." (PMID 36733811, 2022). "Hypermethylation of a CpG island at the GSTP1 promoter leading to loss of GSTP1 expression in prostate cancer was one of the first examples of epigenetic gene silencing in human cancers." (PMID 35104804, 2022). "In the process of prostate carcinogenesis, silence of GSTP1 via hypermethylation is an early and common event and functional inactivation of GSTP1 enhanced the susceptibility to oxidative stress and the risk of prostatic cancer progression." (PMID 35637965, 2022). "Glutathione S-transferase pi 1 (GSTP1) is the most-characterized hypermethylated gene in prostate cancer; it encodes an enzyme that detoxifies reactive electrophilic intermediates." (PMID 33628338, 2021). "Prostate cancer is the second leading cause of cancer death in men, and key determinants of its cellular phenotype include carcinogen defense (GSTP1), growth factor signaling pathways (NKX3.1, PTEN and p27) and AR60." (PMID 33500463, 2021). "For example, hypermethylation of glutathione S-transferase P (GSTP1) is a hallmark of prostate cancer in humans." (PMID 33499041, 2021). "An interaction between high occupational exposure to PAHs and the glutathione S-transferase polymorphism (GSTP1), a detoxifying gene, has been shown to be associated with an increased prostate cancer risk." (PMID 34154586, 2021).
prostate carcinoma (continued). "We have shown that prostate carcinoma-associated epigenetic biomarkers including GSTP1, RASSF1﻿, RARb and APC are detectable in our cultures to confirm that these primary PDCOs indeed originated from tumor cells." (PMID 34581895, 2021). "Studies in human prostate cancer cells suggest a role for GSTP1 as a caretaker gene whose loss increases cell survival in response to protracted oxidative injury." (PMID 34191807, 2021). "As the accumulation of deleterious mutations should adversely impact the fitness of a tumour, we were intrigued why an increased mutation rate is apparently selected for in prostate cancer via hypermethylation of GSTP1 and GSTM2." (PMID 34871444, 2021). "Gene polymorphisms of GSTM1, GSTT1, GSTO1 rs4925, GSTO2 rs156697, GSTP1 rs1695, and GSTP1 rs1138272 and risk of overall mortality in prostate cancer patients by Cox proportional hazards regression models." (PMID 33937322, 2021). "Methylation or other dysregulation of the glutathione S-transferase (GSTP1) gene and the subsequent loss of GSTP1 expression is found in 70–80% of all prostate cancer cases." (PMID 33076397, 2020). "Our observations complement a previous report that showed GSTP1 inhibition using siRNAs and a pharmacological inhibitor elevated ROS levels and caused DNA damage in prostate cancer cells." (PMID 32526885, 2020). "As such, our results suggest modifying the role of multiple GST polymorphic genes, especially GSTP1, to reduce prostate cancer risk." (PMID 32183092, 2020). "The aim of the study was frequency analysis of GSTM1, GSTT1, and GSTP1 polymorphisms of glutathione S-transferase in the group of patients with prostate cancer and in a control group of healthy individuals." (PMID 32212077, 2020). "The results of this study have shown that men with at least one copy of the variant GSTP1 allele rs1138272 (*Ala/Val + Val/Val) or GSTP1 rs1695 (*Ile/Val + Val/Val) are at a significantly higher risk of prostate cancer." (PMID 32183092, 2020). "Since the relationship between GSTP1 polymorphisms, Hg exposure and the risk of prostate cancer seems biologically plausible, it merits future studies in a larger population." (PMID 32183092, 2020). "It should be noted that GSTP1 rs1695 polymorphism, based on several meta-analyses, is likely to be associated with a risk of prostate cancer, while the data on the association between GSTP1*Ala114Val rs1138272 polymorphism and PC risk are scarce." (PMID 32183092, 2020). "In contrast to GSTP1*Ile105Val rs1695 polymorphism, the modifying effect of GSTP1*Ala114Val rs1138272 polymorphism on the risk of prostate cancer has been investigated in only two studies." (PMID 32183092, 2020). "The association between GSTP1 methylation and prostate cancer was present in both Wards, even if confidence intervals were wide in Ward II due to a smaller sample size." (PMID 31666119, 2019). "GSTP1 expression is inactivated in prostate cancers, and this inactivation is associated with hypermethylation of GSTP1 CpG islands." (PMID 29344347, 2018). "Clinically, higher GSTP1 promoter methylation was found to be independently associated with the risk of prostate cancer; therefore, the detection of hypermethylated GSTP1 in urine and semen samples can be a diagnostic marker of prostate cancer." (PMID 29344347, 2018). "Very high levels of GSTP1 methylation are also seen in prostate cancer, which is another male cancer that can be associated with BRCA2 mutation." (PMID 28893223, 2017). "Some of the DNA methylation-based epigenetic biomarkers, such as the methylation status of VIM and SEPT9 for colorectal cancer, SHOX2 for lung cancer, and GSTP1 for prostate cancer, are in clinical use and diagnostic kits are commercially available." (PMID 27895806, 2016). "GSTP1 gene promoter methylation is widely characterized by several independent groups and is found to be have diagnostic value as a biomarker in prostate cancer patient tissue or body fluid aided in non-invasive detection." (PMID 24664224, 2014).
prostate carcinoma (continued). "Individuals with homozygous genotypes of GSTP1 Ile/Ile were reported to have the lowest risk of prostate cancer, and this genotype is found to be protective in rheumatoid arthritis and basal cell carcinoma." (PMID 25606397, 2014). "Currently, the most extensively studied methylation-based markers in prostate cancer are the hypermethylated glutathione S-transferase P1 (GSTP1) and Ras-association domain family protein isoform A (RASSF1A)." (PMID 24877145, 2014). "Since progressive GSTP1 hypermethylation is a hallmark biomarker but potentially also a driver of prostate cancer progression, various research teams were looking for dietary intervention to lower the methylation burden of GSTP1 gene promoter." (PMID 25076909, 2014). "Today GSTP1 hypermethylation is most frequently evaluated as diagnostic biomarker for prostate cancer." (PMID 23957008, 2013). "On the whole, the results about the association between GSTP1 Ile105Val polymorphism and prostate cancer risk were conflicting and inconclusive." (PMID 23977100, 2013). "In subgroup analyses, the significant association of GSTP1 105Val allele with low-stage prostate cancer risk was observed." (PMID 23977100, 2013). "Men with germ line mutation of Tumor suppressor gene BRCA2 have a 20 fold increased risk of prostate cancer while the most common alteration in prostatic cancer is hypermethylation of glutathione S-trasferase (GSTP1) gene which down-regulates GSTP1 expression." (PMID 24063260, 2013). "In recent years, the association of GSTP1 Ile105Val polymorphism with prostate cancer risk has been extensively investigated." (PMID 23977100, 2013). "The present meta-analysis, including 6,790 prostate cancer cases and 7,375 controls, explored the association of one potentially functional polymorphism in the GSTP1 gene and prostate cancer risk." (PMID 23977100, 2013). "Previous results of the studies on the association of GSTP1 Ile105Val polymorphism with prostate cancer risk were inconclusive." (PMID 23977100, 2013). "Methylation of GSTP1 and RARβ2 promoters was reported in tumor-associated endothelium and stroma of localized human prostate cancer." (PMID 23978847, 2013). "Numerous epidemiological studies have evaluated the association of GSTP1 Ile105Val polymorphism with the risk of prostate cancer." (PMID 23977100, 2013). "Third, no previous studies have systemically evaluated the diagnostic value of measuring GSTP1 promoter methylation in different types of body fluids for prostate cancer diagnosis." (PMID 21654682, 2011). "Coordinated hypermethylation of APC and GSTP1 in early carcinogenesis has been utilized as potential diagnostic markers to detect prostate cancer." (PMID 20062804, 2010). "DNA methylation has been implicated in the silencing of the GSTP1 gene in human prostate cancer, and similarly DNA-methylation silencing of several other genes are also implicated in TRAMP prostate tumor." (PMID 20062804, 2010). "Our results suggest a possible association between the GSTP1 Val/Val genotype and the occurrence of prostate cancer." (PMID 19265530, 2009). "Inheritance of at least one GSTP1 105 Val allele (linked with decreased capacity to conjugate electrophilic compounds) was associated with a 1.6-fold increase in prostate cancer risk (OR = 1.56; 95%CI = 0.95-2.58; p = 0.049)." (PMID 19917083, 2009). "Common chemicals are metabolized by GSTP1 and have been associated with risk to develop diseases like non-Hodgkin's lymphoma, hepatocellular and prostate carcinoma, as well as Alzheimer." (PMID 17291352, 2007). "Since the knowledge about the close association of GSTP1 CpG island hypermethylation and prostatic carcinogenesis, an increasing number of studies evaluated its potential as prostate cancer biomarker." (PMID 16803634, 2006). "Besides, loss of GSTP1 expression in prostate cancer cells led to increased ROS levels and DNA damage." (PMID 40342074, 2025).